DSG3 (desmoglein 3)
Diseases named in the same sentence as DSG3 in open-access papers (continued):
Sharing a sentence is not in itself a finding about the gene and the disease.
tumor (31 papers, 2004 to 2025). "DSG3 enhances the diagnostic panel by providing distinct membranous staining, particularly along cell junctions in tumor nests." (PMID 40427131, 2025). "DSG3 is often upregulated in SCCs, and its overexpression has been associated with increased tumour invasiveness and metastasis." (PMID 38067138, 2023). "Lower levels of DSG1, DSG3, and desmosome expression cause the loosening of desmosome adhesion, and cells subsequently leave the primary tumour, leading to tumour invasion and metastasis." (PMID 36291586, 2022). "Indeed, DSG3 has been previously evaluated as a diagnostic marker of squamous differentiation in lung and thymus tumor tissues." (PMID 35251162, 2022). "We thus tested whether desmosome compromise associated with Dsg3 deficiency could promote UVB-induced tumor development in the skin." (PMID 23185521, 2012). "This study developed and validated a BM-related risk score model (including DSG3, MET, and PLAU) in PC using multiple public and clinical cohorts, with a good prediction efficiency for the prognosis, tumor immune environment, and therapy response." (PMID 39513120, 2024). "Next, DSG3 has both improved tumor selectivity (AUC = 0.93 and FDR p = 0.065) and safety (Tabula Sapiens score = 9.13 and HPA score = 1.79) over the leading extant targets in HNSC." (PMID 37835579, 2023). "As expected from the combination of the spatial and scRNA sequencing data, we found positive correlations between the expression of INHBA and collective migration marker genes (CLDN4, NECTIN1, and DSG3) at the tumor-stroma interface." (PMID 35986012, 2022). "As a result, the majority of specimens were biopsies rather than resection specimens, which potentially led to either overestimation or underestimation of the heterogeneity of DSG3 expression in the tumor." (PMID 35251162, 2022). "Other signature genes (TP63, CERS3, CSTA, CLCA2, DSC3 and DSG3) upregulated in C1 tumours are also markers of the squamous-like subtype, while further columnar-like marker genes (MUC5B and RGL3) are upregulated in C2 tumours." (PMID 36207323, 2022). "Defucosylated anti-human DSG3 antibody showed anti-tumour activity against three differential SCC cell lines in xenograft models." (PMID 30239818, 2018). "A reduction in tumour formation and growth was observed in mice injected with Dsg3−/− keratinocytes compared with control group injected with Dsg3+/− keratinocytes." (PMID 25629808, 2015). "Despite the traditional view of DSMs as tumour suppressors and the contribution of Dsg3 in desmosomal adhesive function, recent studies have discovered that Dsg3 is upregulated in SqCC of the head and neck, lung, skin and oesophagus etc.." (PMID 25629808, 2015). "DSG3 over-expression confers the recruitment of plakoglobin, resulting in the reduction of plakoglobin's tumor suppressive function." (PMID 23737966, 2013). "These cellular results were confirmed using tumor xenografts in mice, as DSG3 silencing led to the suppressed tumor growth, plakoglobin translocation and reduced expression of TCF/LEF target genes in tumors." (PMID 23737966, 2013). "We concluded that all evaluated candidates except DSG3 seemed to have good potential as tumor cell markers in patient LNs and PB samples, according to expression level differences between tumors and the sample type of interest." (PMID 23671585, 2013). "Thorough validation in clinical samples revealed that KRT19, CEACAM5, SFTPA, SFTPC and DSG3 were promising markers for tumor cells in LNs and PB from NSCLC patients." (PMID 23671585, 2013). "While tumor histology was similar in the two cohorts, the tumors derived from transformed Dsg3−/− keratinocytes showed a clearly reduced volume compared to tumors derived from transformed Dsg3+/− keratinocytes." (PMID 23185521, 2012).
tumor (continued). "First, using Dsg3−/− keratinocytes, we show that these cells display adhesion defects in vitro and compromised tumor growth in allograft assays, suggesting that Dsg3 enables tumor formation in certain settings." (PMID 23185521, 2012). "We first analyzed tumor development in an allograft model in which transformed keratinocytes with differing Dsg3 status were implanted subcutaneously into immunocompromised mice." (PMID 23185521, 2012). "The two downregulated genes in tumours were sFRP and desmogelein 3 (DSG3); the upregulated gene was identical to the sequence of hPGFS and KIAA0119, according to the BLAST search from gene bank." (PMID 14997212, 2004). "Since the DSG3 cDNA is 7 kb and it was difficult to obtain a high-quality Northern blot result from the total RNA isolated from tumour tissues, we plan to characterise it in the future using a different method." (PMID 14997212, 2004). "Dsg3 may support the tumor microenvironment by influencing collagen deposition and facilitating tumor progression." (PMID 40558105, 2025). "Tumor resection induced transient remission, but postoperative recurrence required rituximab therapy, achieving sustained clinical and serologic improvement (anti‐Dsg3 decline to 60 U/mL)." (PMID 41179602, 2025). "In addition, RNAi-mediated DSG3 silencing reduced xenograft tumor growth and metastasis in HNC cell lines." (PMID 34203070, 2021). "As we were able to generate an anti-mouse DSG3 antibody with the potential of anti-tumour ADCC activity but no pathogenic activity to normal tissues, we examined the proof of concept in a syngeneic mouse model of a mouse lung SCC cell line, LC12." (PMID 30239818, 2018). "In this study, we have found that some SCC cases express higher levels of DSG3 than non-tumour." (PMID 30239818, 2018). "However, this tumor suppressor role is controversial as in vivo analysis of transformed Dsg3−/− keratinocytes showed impaired tumor growth, thereby suggesting an alternative tumor promoting role for desmosomal cadherins." (PMID 24896103, 2014). "All selected markers except DSG3 were present at high levels in the primary tumors and at very low or non-detectable levels in normal LNs and PB in the first round of validation, indicating a potential for detecting tumor cells in NSCLC patients." (PMID 23671585, 2013). "Alternatively, another explanation for the lack of tumor predisposition in Dsg3−/− mice is that desmogleins function differently from Perp and do not play roles as tumor suppressors." (PMID 23185521, 2012). "In vitro, Dsg3 null keratinocytes have a clear defect in cell-cell adhesion compared to wild-type cells, and interestingly, transformed Dsg3−/− keratinocytes form smaller tumors than transformed control keratinocytes in allograft tumor assays." (PMID 23185521, 2012). "Our observation that Dsg3 deficiency in transformed mouse keratinocytes impairs allograft tumor growth suggests that, in certain settings, Dsg3 may have oncogenic activity." (PMID 23185521, 2012). "The results from the mouse studies showed the possibility that antibodies with anti-tumour activity and no PV-like pathogenic activity could be generated, so we proceeded to generate an anti-human DSG3 antibody with similar features." (PMID 30239818, 2018). "The downregulated gene GIMAP1, with a hazard ratio (HR) < 1, was regarded as a tumor suppressor, while the upregulated genes ANO1, DSG3, and SPINK1, with a HR > 1, were considered oncogenes." (PMID 33901011, 2021). "The mRNA expression of SPINK1, DSG3, ANO1 were significantly increased in PAAD tumor tissue while GIMAP1 were significantly decreased compared with normal tissues." (PMID 33901011, 2021). "Nevertheless, as suggested in a recent report, it is likely that DSG3 is not required for tumour initiation but plays an important role in metastasis." (PMID 38067138, 2023).
tumor (continued). "The up-regulated genes such as DSG3 and LGR5 might facilitate tumor metastasis, while the downregulation of ITGA3 changed the extracellular matrix and might promote tumor expansion." (PMID 34222020, 2021). "To confirm the proof of concept in non-clinical models, we attempted to generate an anti-mouse DSG3 mAb that has anti-tumour activity by ADCC to SCC, but with no cell–cell dissociating effects in keratinocytes that cause PV." (PMID 30239818, 2018). "Collectively, these studies suggest that the ablation of Dsg3 does not appear to promote tumour development, implying Dsg3 does not possess tumour suppressive ability." (PMID 25629808, 2015). "The lack of tumor suppressor activity of Dsg3 we observed is consistent with certain previous reports about the role of DSG3 in human carcinogenesis." (PMID 23185521, 2012). "Unexpectedly, there was no enhanced tumor development in Dsg3−/− mice relative to controls after chronic UVB treatment, in contrast to our previous observation that Perp deficiency in the epidermis promotes SCC development." (PMID 23185521, 2012). "Quantification failed to reveal, however, a difference in apoptotic indices in the epidermis of UVB-treated Dsg3 null and wild-type mice, suggesting a rationale for the lack of enhanced tumor phenotype in UVB-treated Dsg3−/− mice." (PMID 23185521, 2012). "Furthermore, one of the DSG3 antibodies showed anti-tumour activity in tumour mouse models but did not induce adverse effects such as blister formation in the skin." (PMID 30239818, 2018). "All anti-skin antibodies were significantly higher in the EB patients than in the controls (p = 0.008, p < 0.001, p < 0.001, p < 0.001 and p < 0.001 for desmoglein 1 (DSG1), desmoglein 3 (DSG3), bullous pemphigoid 180 (BP180), BP230 and type VII collagen (COL7), respectively)." (PMID 27669234, 2016). "Serum anti-skin antibodies were significantly higher in the patients than in the controls (p = 0.008, p < 0.001, p < 0.001, p < 0.001 and p < 0.001 for desmoglein 1 (DSG1) desmoglein 3 (DSG3), bullous pemphigoid 180 (BP180), BP230 and type VII collagen (COL7), respectively)." (PMID 27669234, 2016). "The upregulation of Dsg1 and 2 upon Dsg3 loss may compensate for deficiency in some Dsg3 functions and could explain the lack of phenotypes in the UVB-induced tumor model." (PMID 23185521, 2012). "One revelation was the downregulation of an apoptosis candidate gene, sFRP, and a tumorigenesis suppressor gene, DSG3, in SCCHN that are also found by other investigators in other tumour tissues, demonstrating that different tumours may share a common molecular mechanism in tumorigenesis." (PMID 14997212, 2004). "After five weeks, at which time mice were sacrificed and tumor volume was calculated, all mice injected with transformed Dsg3+/− keratinocytes developed tumors, whereas only 80% of the mice injected with transformed Dsg3−/− keratinocytes developed tumors (data not shown)." (PMID 23185521, 2012). "Similarly, the average tumor size was not clearly different between Dsg3 null and wild-type mice." (PMID 23185521, 2012).
infection (4 papers, 2014 to 2024). The state of being infected such as from the introduction of a foreign agent such as serum, vaccine, antigenic substance or organism. "Analysis of somatic hypermutations (SHMs) in these rearrangements showed that Dsg3-specific MBCs are highly mutated, comparable to infection-induced plasmablasts." (PMID 31340153, 2019).
inflammation (1 paper, 2019). Aberrant reaction of the microcirculation characterized by movement of fluid and leukocytes from the blood into extravascular tissues. "Moreover, adoptive transfer of Dsg3-specific CD4+ T cells in RAG2−/− mice induced pulmonary inflammation and ectopic Dsg3 expression." (PMID 31214197, 2019).
lung (1 paper, 2020). "Materials and methods: We compared the usefulness of six conventional (CK5/6, p40, p63, CK7, TTF1, and Napsin A) and three novel (PKP1, KRT15, and DSG3) markers to distinguish between lung SCC and AC in 85 small biopsy specimens (41 ACs and 44 SCCs)." (PMID 31809668, 2020).
DSG3 also shares sentences with these, for which no sentence is quoted: adenocarcinoma (5 papers); cutaneous melanoma (2); lymphoma (2); pneumonia (2); bladder cancer (1); cardiomyopathy (1); cervical cancer (1); cervical intraepithelial neoplasia (1); chronic inflammatory demyelinating polyneuropathy (1); colon cancer (1); colorectal adenocarcinoma (1); cutaneous T-cell lymphoma (1); erythroderma (1); female infertility (1); gingivitis (1); glioblastoma (1); head and neck tumors (1); herpes zoster (1); inflammatory bowel disease (1); inverted papilloma (1); Keratin (1); lichen planus (1); malnutrition (1); oral disease (1); Oral leukoplakia (1); pancreatic ductal adenocarcinoma (1); pemphigus erythematosus (1); pemphigus vegetans (1); pulmonary alveolar proteinosis (1); seborrheic dermatitis (1).
A further 10 diseases each share a sentence with DSG3 in 1 paper.